IL4R (interleukin 4 receptor)
Diseases named in the same sentence as IL4R in open-access papers (continued):
Sharing a sentence is not in itself a finding about the gene and the disease.
infection (continued). "Re-infection of B cell-specific IL-4Rα−/− mice resulted in increased worm burdens compared to control mice, despite their equivalent capacity to control primary infection." (PMID 24204255, 2013). "Here, the significantly higher intestinal worm burden at day 5 secondary infection in IL-13−/− mice compared to IL-4−/− mice, demonstrated IL-13 signalling through IL-4Rα is essential for immunity against re-infection with N. brasiliensis." (PMID 24204255, 2013). "It has also been shown that global abrogation of IL-4Rα renders mice resistant to L. major only in the acute phase of infection, with mice continuing to develop necrotic footpad lesions during the chronic phase." (PMID 24204259, 2013). "As expected, genetically resistant C57BL/6 mice effectively controlled infection, as did global IL-4Rα-/- mice, which have been shown to be resistant during the acute phase of L. major infection, with disease progression in the chronic phase only." (PMID 24204259, 2013). "Strikingly, IL-4Rα expression was higher in BALB/c WT mice infected with VV-HA-IL-4 relative to VV-HA infection when comparing naïve (GzmB− CD62L+) or effector (GzmB+ CD62L−) CD8+ T cells." (PMID 23383283, 2013). "As IL-4Rα−/− mice exhibit a strongly impaired antibody response during primary and challenge infections with Hp, we treated challenge-infected mice with immune serum (collected at day 4 p.i.)from immune C57BL/6 mice." (PMID 24244174, 2013). "Secondary infection resulted in a significantly higher intestinal worm burden in MB1CreIL-4Rα−/lox mice when compared to IL-4Rα−/lox mice." (PMID 24204255, 2013). "IL-4Rα−/− mice had significantly higher intestinal worm burdens compared to IL-4Rα−/lox mice at day 5 or 7 post-secondary infection." (PMID 24204255, 2013). "Several studies, including our own, have demonstrated a correlation between the presence of IL-4Rα+ macrophages and enhanced eosinophilic inflammation using infection and allergic models in mouse and man." (PMID 22292924, 2012). "Worms recovered 70 days post infection in IL-4R/IL-5 DKO mice were young adults and measured 10.12 mm in length and 0.1 mm in width." (PMID 22348321, 2012). "Whereas total IgE antibody concentration was below detection limit in the sera of global IL-4Rα−/− mice, IgE antibodies were present in naive iLckcreIL-4Rα−/lox mice and increased during infection, though to a lesser extent than infected control mice." (PMID 23284939, 2012). "Heterozygous IL-4Rα−/lox control and iLckcreIL-4Rα−/lox mice showed similar egg production throughout the infection with egg counts peaking at day 7 and clearing by day 9 post infection (PI)." (PMID 23284939, 2012). "Since the original Th1/Th2 dichotomy emerged, it has become clear that in most instances resistance to infection requires a concerted Th2 response, dependent upon the nexus of IL-4Rα-mediated signalling." (PMID 22795966, 2012). "The strain that best accommodated L. loa was the IL-4R-/-/IL-5-/- KO with larvae surviving up to 70 days post infection." (PMID 22348321, 2012). "These infections are characterised by IL-4Rα-driven responses which are essential for worm expulsion from the host intestine." (PMID 23284939, 2012). "Parasite numbers at the termination of the study at week 12 were of a similar order of magnitude in both female and male control IL-4Rα−/lox mice while global IL-4Rα−/− mice of both sexes were equally able to control infection with L. mexicana." (PMID 21245915, 2011). "In subsequent studies, infection of CD4+ T cell specific (LckcreIL-4Rα−/lox) IL-4Rα−/− mice with 5×106L." (PMID 21245915, 2011). "Our data show an up-regulation of the IL-4 receptor (IL4R) during the challenge infection indicative of a Th2-type response." (PMID 20950493, 2010). "The interleukin 4 receptor (IL4R) was consistently up-regulated when either Challenge infection 1 or 2 pools were compared to the Pre-infection pool." (PMID 20950493, 2010).
infection (continued). "Median survival times were 20, 25, and 23 days post C. neoformans strain H99γ infection for IL-12p40, IL-12p35, and IFN-γ deficient mice, respectively (P<0.0001 compared to immune competent BALB/c and IL-4R deficient mice)." (PMID 19727388, 2009). "Infection of IL-4Rα-/- mice results in considerably higher worm burdens (approx. 251 worms/caecum at day 28 PI and 400 worms/caecum at day 35 PI) when compared to wild type mice." (PMID 18373844, 2008). "Of note, IL-13Rα1 but not IL-4Rα mRNA levels were decreased upon Elp3 deficiency 7 days post-infection." (PMID 39085648, 2024). "IFN-γ in response to double infection was reduced in the LysMCre IL-4Rα KO." (PMID 36032072, 2022). "Confirming the importance of type 2 immunity in filarial lymphatic pathology, IL-4R–deficient mice did not develop significant remodeling and were protected from lymphatic dysfunction after infection." (PMID 33434186, 2021). "To our surprise, using a combination of in vivo approaches, including transgenic mice (IL4Rαfl/fl.CX3CR1Cre) and mixed bone marrow chimaeras, we found that during infection driven inflammation, IL4Rα on colonic macrophages was completely dispensable for the emergence of RELMα+Ym1+ macrophages." (PMID 34329367, 2021). "More importantly, the loss of IL-4Rα signaling on CD11c+ DCs did not affect the production of nitrite and urea (in ex vivo infection of BMDCs), which are known substrate for iNOS and arginine-derived metabolite respectively." (PMID 35154068, 2021). "However, IL-4Rα signalling appears to depend on the Leishmania species/sub-species initiating infection as L. major infection was also unchanged in IL-4/IL-4Rα-deficient mice." (PMID 33415318, 2020). "In one group of mice IL-4Rα was blocked using monoclonal antibodies prior to a primary infection with 50 metacercariae; a second group of mice was treated with rIL-13Rα2 prior to the infection; a third group of rIL-25-treated mice were exclusively infected with 50 E." (PMID 33276813, 2020). "It is therefore possible that longer-term primary infections might resolve the relative roles of IL-4Rα, IL-5, and CCR3 in eosinophil-mediated control of circulating mf." (PMID 32571840, 2020). "Because immune resistance to filarial infection is dependent on a sustained influx of eosinophils mediated by the CCR3-CCR3 ligand chemokine pathway, the levels of Siglec F+ eosinophils in the peritoneal infection site were compared between WT, IL-4Rα−/−, and CCR3−/− mice." (PMID 32571840, 2020). "However, later post-infection, CD4+ T cell specific IL-4Rα-deficient mice and wild-type controls had equivalent parasite burdens in the spleen, liver and bone marrow as well as a similar hepatic granulomatous response." (PMID 31475014, 2019). "Indeed, at day 30 post-infection CD4+ T cell as well as pan T cell-specific IL-4Rα−/lox mice (iLckcreIL-4Rα−/lox) were more." (PMID 31475014, 2019). "IL-13−/− and IL-4Rα−/− groups developed lesions similar to wild type upon initial infection." (PMID 30759882, 2019). "In summary, L. major parasites may use Ly6C+CD11b+ inflammatory DCs derived from monocytes recruited to infection as “Trojan horses” to migrate to secondary lymphoid organs and peripheral sites, and DC IL-4Rα expression is important for controlling infection." (PMID 32039054, 2019). "However, by day 6 post-infection, IL-4Rα-dependence of RELMα expression was evident in the airway epithelium, and areas of RELMα positivity were significantly reduced in lungs from Il4ra-/- compared to wild-type mice." (PMID 30500858, 2018). "Similarly, infection of our Foxp3cre IL-4Rα−/lox mice resulted in elevated inflammatory responses in helminth-mediated disease models." (PMID 30379806, 2018). "The emerging principles of innate instruction of adaptive immunity further exemplify that IL-4Rα signaling on innate cells may contribute specific functions that shape the adaptive immune response and outcome of infection." (PMID 29176972, 2017).
infection (continued). "However, in contrast to IL-4−/− mice, IL-4Rα−/− mice developed progressive disease and necrotic footpad lesions during the chronic phase of infection." (PMID 29176972, 2017). "Similarly, the viability of Tam2- and Tam6-fed RosaCreERT2-/+IL-4Rα-/lox mice declined rapidly (60 and 50% respectively at week 8 post-infection)." (PMID 28827803, 2017). "S. mansoni-infected mice following IL-4Rα knockdown at 16 weeks post-infection, i.e. iCre-/+IL-4Rα-/lox Tam16 mice did not result in any weight loss or mortality, for up to 24 weeks post infection." (PMID 28827803, 2017). "We show that sustained expression of IL-4Rα is required for the maintenance of type 2 immune responses and protective immunity following interruption after polarization with Nippostrongylus brasiliensis primary infection." (PMID 28651009, 2017). "Interestingly, despite the presence of IL-4Rα early during infection, timely interruption of IL-4Rα mediated signaling after 6 days of infection impaired worm clearance in iCre-/+IL-4Rα-/Lox mice similarly to IL-4Rα-/- mice that lacked the receptor from birth." (PMID 28651009, 2017). "Moreover, we show by temporal deletion of IL-4Rα prior to secondary infection with N. brasiliensis that signaling via this receptor drives more efficient recall of type 2 immune responses and clearance of the parasites." (PMID 28651009, 2017). "In the course of an infection with gut nematodes, signaling via the IL-4Rα has been shown to be critical in the initiation and the development of protective Th2 immunity against primary infection and in the development of an optimal memory Th2 response to counter secondary infections." (PMID 28651009, 2017). "As expected, from our previous mortality studies, body weights of S. mansoni-infected IL-4Rα-/- and iCre-/+IL-4Rα-/lox Tam2 mice rapidly declined starting 6 weeks post-infection that preceded the death of these animals when compared to IL-4Rα-responsive control mice." (PMID 28827803, 2017). "By disrupting the host ability to maintain pre-established Th2 immune responses during primary N. brasiliensis infection and clear the infection, the interruption of IL-4Rα mediated signaling reveals a unique role of this signaling axis in the maintenance of anti-nematode Th2 immune responses." (PMID 28651009, 2017). "Infection studies with L. major LV39 and IL-81 in B cell-specific IL-4Rα-deficient BALB/c mice revealed a beneficial role for IL-4Rα-unresponsive B cells in host-protective immunity and concomitantly, a detrimental role for IL-4Rα-responsive B cells in the non-healing response to L. major." (PMID 29176972, 2017). "In this study, we show that the temporal impairment of IL-4Rα mediated signaling disrupts already established Th2 immune responses during primary and secondary infections with the model nematode Nippostrongylus brasiliensis and limit the host ability to expel the worms." (PMID 28651009, 2017). "From Tam-2-fed, Tam-6 fed or IL-4Rα deficient mice, no death was further reported as from 12 weeks post-infection, at the chronic phase of the disease." (PMID 28827803, 2017). "However, mice on the C57BL/6 genetic background with total abrogation of IL-4Rα on all cells were fully able to control lesion size and parasite load following either intradermal or subcutaneous infection with 2 × 105L." (PMID 29067025, 2017). "Because of the clear recruitment of Ly6C+ monocytes to the intestine following challenge, and the requirement for IL-4R-dependent alternatively activated macrophages (AAMs) in resistance to secondary infection with H. polygyrus, we vaccinated and challenged CCR2-/- mice." (PMID 25816012, 2015). "In the experiments presented here, IL-4Rα−/− mice unexpectedly show decreased fungal control early upon infection with C. neoformans, whereas wild-type mice are able to control fungal growth accompanied by enhanced macrophage and dendritic cell recruitment to the site of infection." (PMID 24475277, 2014).
infection (continued). "We show that, in contrast to the late Th2-driven phase of infection, within the first two weeks of infection IL-4Rα signaling is able to elicit potent macrophage and dendritic cell recruitment and elevated production of IFN-γ and nitric oxide associated with better fungal growth control." (PMID 24475277, 2014). "IL-4 can induce the activation of STAT1, STAT3, STAT5 and STAT6 on naïve and activated CD8+ T cells in vitro, but our infections studies with VV-HA-IL-4 indicated that STAT6 was indispensible for IL-4 mediated up-regulation of cell surface IL-4Rα expression on naïve and effector CD8+ T cells." (PMID 23383283, 2013). "We therefore tested in vivo whether immunity induced early in infection with N. brasiliensis is dependent on IL-4Rα-responsive B cells." (PMID 24204255, 2013). "Similarly, reduction in cell surface IL-4Rα expression on CD8+ T cells following VV-WR infection was detected on day 5 p.i., peaked on day 7 p.i. and declined from days 14–28 p.i.." (PMID 23383283, 2013). "However, infection with N. brasiliensis showed increased tension at day 7 and 10 in control IL-4Rα−/lox mice compared to global IL-4Rα−/− and iLckcreIL-4Rα−/lox mice." (PMID 23284939, 2012). "Furthermore, IL-4Rα-mediated signalling activates smooth muscle cells, leading to hypercontractibility during infection, while also stimulating Th2-promoting cytokine production from muscle cells." (PMID 22795966, 2012). "Larvae recovered 70 days post infections in IL-4R-/-/IL-5-/- DKO were from the heart and muscles." (PMID 22348321, 2012). "Although signaling via IL-4Rα plays a significant role in the outcome of infection with L. mexicana as well as L. major the cell targets for IL-4/IL-13 activity and whether they promote or inhibit the disease process differ significantly between species." (PMID 21245915, 2011). "Infections of IL-4-/-, IL-13-/-, IL-4Rα-/- and Stat 6-/- mice with the nematodes Trichuris muris, Heligmosomoides polygyrus and Nippostrongylus brasiliensis have demonstrated a positive relationship between polarisation to a TH2 immune response, goblet cell hyperplasia and worm expulsion." (PMID 18373844, 2008). "However, in the current study, we identify that control of chronic adult filarial worm infection is evident in IL-4Rα–deficient (IL-4Rα−/−) mice, whereby the majority of infections do not achieve patency." (PMID 32571840, 2020). "Because distinct immune responses are triggered against different life cycle stages of filarial parasites, we scrutinized whether either IL-4R–dependent or IL-4R–independent/CCR3- or IL-5–dependent immunity was also operating at the level of stage-specific mf infections." (PMID 32571840, 2020). "Here we expand on these findings and show that CD4+ T cell-(Lckcre), as well as pan T cell-(iLckcre) specific IL-4Rα deficient mice, on a BALB/c background, unlike global IL-4Rα deficient mice, are also not adversely affected in terms of resistance to primary infection with L. donovani." (PMID 31475014, 2019). "Hence, we investigated whether a change in the site of infection and parasite dose would alter the phenotype and immune response of the KRT14cre IL-4Rα−/lox BALB/c mice." (PMID 30275010, 2018). "However, the body weights of S. mansoni-infected iCre-/+IL-4Rα-/lox Tam6 mice rapidly declined following Tamoxifen-driven removal of IL-4Rα at 6 weeks post-infection similar to IL-4Rα-/- mice and culminated into the early death of these animals, when compared to IL-4Rα-responsive control mice." (PMID 28827803, 2017). "Accordingly, IL-4Rα-deficient BMDCs, with reduced IL-12 and increased IL-10 secretion, failed to vaccinate BALB/c animals against acute leishmaniasis, while IL-4-sufficient BMDCs producing increased IL-12 and reduced IL-10 successfully immunized BALB/c mice against infection." (PMID 29176972, 2017).
infection (continued). "However following infection of IL-4Rα-/- mice, which are compromised in their capacity to generate a Th2 response, they found similar changes in the gut microbiota composition, indicating that the hookworm was able to alter the microbiota independently of the IL-4-regulated adaptive Th2 response." (PMID 25942314, 2015). "The IL-4Rα-dependent increased nitric oxide concentration in supernatants from ex vivo stimulated lung leukocytes together with the elevated IFN-γ expression in WT mice point to a potential mechanism by which the immune system can reduce the fungal growth in the first two weeks after infection." (PMID 24475277, 2014). "Lastly, we sorted myeloid cells from the livers of infected IL-4Rαflox/ΔLysMCre mice and IL-4Rαflox/Δ littermate controls to confirm that there are macrophages resistant to Il4rα excision during active infection in the liver and to discern whether Lyz2 expression was responsible for this." (PMID 25211233, 2014). "When analyzing these leukocyte subpopulations, we observed a comparable increase in the number of Th cells in WT and IL-4Rα−/− mice, whereas the number of alveolar macrophages and dendritic cells was significantly higher in WT as compared with IL-4Rα−/− mice at 14 days after infection." (PMID 24475277, 2014). "Blocking of IL-4Rα in mice treated with rIL-25 induced a decline in STAT6 phosphorylation and a Th1 response to infection." (PMID 33276813, 2020). "Given the pleiotropic nature of the IL-4Rα, these IL-4Rα-responsive cells could of course be different populations in different tissue sites and could vary for different type of immune responses e.g., primary infection, response to chemotherapy or successful vaccination." (PMID 31475014, 2019). "Immunodeficient mice (IL-4R−/−, IL-5−/−, IL-4R−/−/IL-5−/−, dblGATA BALB/c mice) exhibited increased numbers of peripheral MF throughout the infection compared to WT controls." (PMID 31109364, 2019). "Therefore, we can only speculate that the amelioration of plaque-type psoriasis upon IL-4 treatment and the decrease in infections in type 2 diseases upon IL-4R signaling blockade is, at least in part, the direct result of increased or decreased IL-4R signaling on neutrophils, respectively." (PMID 31708926, 2019). "Despite a significant decrease in parasite burden seen at the site of infection after i.d. inoculation of L. major LV39, KRT14cre IL-4Rα−/lox mice on the BALB/c genetic background still developed a nonhealing response." (PMID 30275010, 2018). "Following infection with L. major LV39 for 8 weeks, cell populations infiltrating the draining cervical lymph nodes were similar between KRT14cre IL-4Rα−/lox BALB/c and littermate control IL-4Rα−/lox BALB/c mice." (PMID 30275010, 2018). "Thirty days post infection, the cell populations expressing MHC class II, IL-4R and Dectin-1 were increased, but those expressing the costimulatory receptor CD86, and MR or CD23 were reduced." (PMID 29156562, 2017). "Infection of these mice with another strain of L. major (IR173) resulted in partial control of lesion size in IL-4−/− mice, while IL-4Rα−/− controlled lesion size efficiently." (PMID 29067025, 2017). "In this model, we also found that some genes exhibited a downward trend (e.g., Ptgs2, Rel, IL4r, CXCL1, CXCL2, TLR5, Nfatc3 and Egr2) in M. fortis after infection." (PMID 28900150, 2017). "The total numbers of DX5+ NK cells were not altered significantly in GKO strains compared with WT mice following infection with ECTV-WT, with the exception of the IL-13−/−/IL-4Rα−/− mice in which the numbers were about 5-fold lower." (PMID 25751266, 2015). "VV-HA-IL-4 infection studies showed that IL-4 and STAT6 was required to up-regulate IL-4Rα expression on naïve and effector CD8+ T cells." (PMID 23383283, 2013). "IL-4R-/-/IL-5-/- DKO supported the infection better than any other strain (70 days), followed by IL-5-/- KO (50 days), IFN-γ-/-/IL-5-/- DKO (40 days), IFN-γ-/- KO (20 days) and lastly IL-4R-/- KO (5 days)." (PMID 22348321, 2012).